CALM2 (calmodulin 2)
Description:
Calmodulin acts as part of a calcium signal transduction pathway by mediating the control of a large number of enzymes, ion channels, aquaporins and other proteins through calcium-binding. Calcium-binding is required for the activation of calmodulin. Among the enzymes to be stimulated by the calmodulin-calcium complex are a number of protein kinases, such as myosin light-chain kinases and calmodulin-dependent protein kinase type II (CaMK2), and phosphatases. Together with CCP110 and centrin, is involved in a genetic pathway that regulates the centrosome cycle and progression through cytokinesis. Mediates calcium-dependent inactivation of CACNA1C. Positively regulates calcium-activated potassium channel activity of KCNN2. (Microbial infection) Required for C.violaceum CopC and S.flexneri OspC3 arginine ADP-riboxanase activity.
Synonyms: PHKD; PHKD2; CAMII; CALM; CALML2; CAM1; CAM3; CAMC; CAMIII; LQT15; caM
Tractability: Small molecule: a structure with a bound ligand is known; it belongs to a druggable protein family. Antibody: its Gene Ontology location is reachable by antibodies, with high confidence. PROTAC: UniProt records ubiquitination sites on it.
Gene: Protein-coding gene on chromosome 2 (47,160,084 to 47,176,921, reverse strand). Ensembl gene ENSG00000143933.
Subcellular location: Cytoplasm, cytoskeleton, spindle; Cytoplasm, cytoskeleton, spindle pole; Cytoplasm, cytoskeleton, microtubule organizing center, centrosome
Pathways (Reactome):
Disease: Enterobacterial factors antagonize host defense
Immune System: CASP4 inflammasome assembly
Gene Ontology:
Molecular function: adenylate cyclase activator activity; adenylate cyclase binding; calcium channel inhibitor activity; calcium channel regulator activity; calcium ion binding; protein binding; protein kinase binding; protein phosphatase activator activity; protein serine/threonine kinase activator activity; titin binding; transmembrane transporter binding; calcium-dependent protein binding; transporter inhibitor activity
Biological process: calcineurin-mediated signaling; detection of calcium ion; negative regulation of ryanodine-sensitive calcium-release channel activity; regulation of cardiac muscle contraction; regulation of cardiac muscle contraction by regulation of the release of sequestered calcium ion; regulation of cell communication by electrical coupling involved in cardiac conduction; regulation of cytokinesis; regulation of heart rate; regulation of release of sequestered calcium ion into cytosol by sarcoplasmic reticulum; response to calcium ion; substantia nigra development; G protein-coupled receptor signaling pathway; long-term synaptic potentiation; negative regulation of calcium ion export across plasma membrane; regulation of calcium-mediated signaling; presynaptic endocytosis
Cellular component: calcium channel complex; catalytic complex; centrosome; cytoplasm; nucleus; protein-containing complex; sarcomere; spindle microtubule; spindle pole; vesicle; cytosol; membrane; myelin sheath; plasma membrane; calyx of Held; presynaptic cytosol; sperm midpiece; spindle; voltage-gated potassium channel complex
Genetic constraint (gnomAD): Loss-of-function variants: 0 observed, 11.41 expected, observed/expected ratio (o/e) 0, 90% interval 0 to 0.26. The upper end of that interval is the gene's LOEUF score, 0.26, which puts it in group 1 of 6, group 1 being the genes least tolerant of losing a copy. Missense variants: 29 observed, 147 expected, observed/expected ratio (o/e) 0.2, 90% interval 0.15 to 0.27. Synonymous variants: 37 observed, 45.17 expected, observed/expected ratio (o/e) 0.82, 90% interval 0.63 to 1.08.
Gene-disease validity (ClinGen):
ClinGen rates the evidence that CALM2 causes each of these diseases.
long QT syndrome (autosomal dominant): Definitive.
catecholaminergic polymorphic ventricular tachycardia (autosomal dominant): Moderate. Catecholaminergic polymorphic ventricular tachycardia (CPVT) is a severe genetic arrhythmogenic disorder characterized by adrenergically induced ventricular tachycardia (VT) manifesting as syncope and sudden death.
Homologues: Orthologues: guinea pig Calm2 (100% identical), mouse Calm2 (100% identical), pig CALM2 (100% identical), tropical clawed frog calm1 (100% identical), rat Calm2 (99% identical), zebrafish calm2b (95% identical), chimpanzee CALM2 (94% identical), dog CALM2 (93% identical), rat Calm1 (91% identical), rabbit CALM2 (87% identical), Caenorhabditis elegans cal-1 (66% identical), Caenorhabditis elegans cal-3 (58% identical), and 6 more. Paralogues in human: CALM1 (100% identical), CALM3 (100% identical), CALML3 (85% identical), CETN1 (53% identical), CETN2 (51% identical), CALML5 (50% identical), CALML6 (46% identical), CABP2 (45% identical), CABP4 (44% identical), CABP5 (44% identical), CALML4 (44% identical), CABP1 (43% identical), and 8 more.
Diseases named in the same sentence as CALM2 in open-access papers:
CALM2 is named in the same sentence as 53 diseases in open-access papers, as found by Europe PMC text mining. Sharing a sentence is not in itself a finding about the gene and the disease. The quoted sentences say what the papers report.
cardiac arrhythmia (10 papers, 2016 to 2025). Any disturbances of the normal rhythmic beating of the heart or MYOCARDIAL CONTRACTION. "For example, CALM2, which mRNA was identified in all the samples, has SNPs associated with cardiac arrhythmia and sudden death of young people after exercise." (PMID 34103018, 2021). "CaM mutations were found in five subjects with QT prolongation; nonetheless, two of them (CALM2-p.D132E and –p.Q136P) were associated with arrhythmia features strongly suggestive of SR instability and thus were assigned to the CPVT phenotype." (PMID 30619883, 2018). "Fetus 16 underwent insertion of an implantable cardiac defibrillator due to a significantly prolonged postnatal QTc of 680 ms and subsequent identification of a pathogenic CALM2 mutation known to be associated with a severe phenotype with a high risk of cardiac arrhythmias in early childhood." (PMID 41328558, 2025). "Downregulation of CALM1 is predicted to cause electrical dysfunctions in muscle and is associated with cardiac arrhythmias; however, redundancy exists in the form of CALM2 and CALM3, which may mitigate this effect." (PMID 38793603, 2024). "We validated some key genes by real-time PCR and found Decr1 (an enzyme which participates in fatty acid β-oxidation), Calm2 (associated with cardiac arrhythmias), and Ddit3 (a proapoptotic transcription factor) expressed a statistically significant increase when compare with the control group." (PMID 35464763, 2022). "Thus far the technology is being explored for possible treatment of monogenic disorders, including cardiac arrhythmias caused by mutations in the CALM1, CALM2 or CALM3 genes." (PMID 35459248, 2022).
breast cancer (8 papers, 2010 to 2024). A primary or metastatic malignant neoplasm involving the breast. "Increased levels of CALM2 have been linked to a regulation of cell apoptosis in breast cancer cells." (PMID 31646972, 2019). "BAIAP2 was associated with overall and ER+ breast cancer; CALM2 with overall breast cancer; CSNK2A1 with ER+ breast cancer; and BRAF, BAD, and MAPK3 with ER− breast cancer." (PMID 27942580, 2016). "CALM2, to a large extent, correlates with anaplastic large cell lymphoma, breast cancer, and other diseases." (PMID 34604066, 2021). "As displayed by recent studies, CALM2 exhibits an aberrant expression in breast cancer cells and neuroblastoma, but its certain function in cancer remains a mystery." (PMID 34604066, 2021). "In breast cancer cells, CALM2 directly binds to death receptor-5 (DR5) in a calcium dependent manner leading to the formation of death inducing complex for apoptotic signaling." (PMID 31646972, 2019). "In breast cancer cells, CALM2 directly binds to death receptor-5 (DR5) in a calcium dependent manner leading to the formation of death inducing signaling complex for apoptotic signaling." (PMID 31646972, 2019). "Thus, CALM2 may impact breast cancer susceptibility through its effects on hormone synthesis." (PMID 31646972, 2019). "The most significant gene associations (P⩽0.01) were BAIAP2 and CALM2 for overall breast cancer; BAIAP2 and CSNK2A1 for ER+ breast cancer; and BRAF, BAD, and MAPK3 for ER− breast cancer." (PMID 27942580, 2016). "As expected, knock-down of HuR by shRNA decreased expression of CD9 and CALM2 in ER+ breast cancer (MCF-7)." (PMID 20370918, 2010). "We selected and validated two HuR targets, CD9 and CALM2 mRNAs, which were found in high abundance in both types of breast cancer." (PMID 20370918, 2010). "For CALM2, ORs for SNP rs13032512, with a risk-allele frequency of 5.5% in AMBER controls, were 1.33 (P=1.3×10−4), 1.30 (P=4.1×10−3), and 1.35 (P=8.2×10−3) for overall, ER+, and ER− breast cancer, respectively." (PMID 27942580, 2016). "Furthermore, CALM2 was overexpressed in tumor tissues and correlated with poorer prognosis in patients with breast cancer and TNBC patients in the TCGA and Metabric databases, suggesting that CALM2 gene expression might also account for the malignant behaviors of TRIM1-269aa." (PMID 38755678, 2024). "CALM2 and CALML5 were found to be significantly active in primary breast cancer, whereas CALML3 and CALML6 were significantly active in liver metastasis of breast cancer." (PMID 37958607, 2023). "Calmodulin-like proteins, namely CALM2 and CALM3, were also upregulated in saliva of bitches with mammary tumors." (PMID 32344524, 2020). "We found that CALM2 and CALML5 were significantly active in primary breast cancer, while CALML3 and CALML6 were significantly active in breast cancer liver metastasis." (PMID 31557971, 2019). "The downregulation of CALM2, a calcium binding protein responsible for proliferation, apoptosis, and cell cycle development, as a consequence of BC200 overexpression, may in part explain the phenotypic changes observed in these breast cancer subtypes." (PMID 31646972, 2019).
long QT syndrome (8 papers, 2017 to 2025). "It has been revealed that CALM2 mutation bears a relation to susceptibility to congenital arrhythmia, which has been extensively investigated in LONG QT syndrome." (PMID 34604066, 2021). "Cardiac diseases benefit from dCas9-KRAB’s ability to repress the CALM2 gene in long-QT syndrome, normalising cardiac cellular functions." (PMID 39726634, 2024). "Previous researches have showed that mutation of CALM2 or CALM3 was the main reason for catecholamine-sensitive ventricular tachycardia and long QT syndrome." (PMID 33330659, 2020). "Among the genes associated with long QT syndrome, only AKAP9 and CALM2 are not included in the clinical exome of Illumina." (PMID 28315637, 2017).
catecholaminergic polymorphic ventricular tachycardia (6 papers, 2017 to 2025). "Catecholaminergic Polymorphic Ventricular Tachycardia is an inherited arrhythmogenic disorder of myocardial calcium hemostasis, autosomal dominant form and autosomal recessive form of which may be due to mutations in the ryanodine receptor and calmodulin 2 genes, respectively." (PMID 38167168, 2024). "The hereditary pro-arrhythmic condition catecholaminergic polymorphic ventricular tachycardia (CPVT), is associated with gene mutations involving ryanodine receptor type 2 (RYR2), calsequestrin (CASQ2), triadin (TRDN) or calmodulin (CALM1, CALM2 and CALM3)." (PMID 34643236, 2021).
gastric cancer (6 papers, 2021 to 2025). A primary or metastatic malignant neoplasm involving the stomach. "In gastric cancer, silencing CALM2 can increase sensitivity to afatinib by regulating the AKT/FOXO3A/Puma axis." (PMID 40940943, 2025). "In gastric cancer pathogenesis, elevated expression of CALM2 has been observed in both tissue samples and cell lines." (PMID 40610429, 2025). "It was uncovered that CALM2 was prominently up-regulated in gastric cancer tissues, and CALM2 overexpression considerably enhanced GC cell proliferation and metastasis." (PMID 34604066, 2021). "The enrichment analysis assessed the potential KEGG pathways of CALM2 in STAD, indicating that the Gastric cancer pathway is a promising pathway of CALM2." (PMID 34604066, 2021). "In addition, Calmodulin2 (CALM2) has been found to exhibit high expression in gastric cancer (GC) cells, modulating the JAK2/STAT3/HIF-1/VEGFA axis, promoting macrophage polarization, and facilitating ECs angiogenesis." (PMID 37666809, 2023). "In this study, we intended to research the function and mechanism of Calmodulin2 (CALM2) in gastric cancer (GC)-TAM microenvironment." (PMID 34604066, 2021). "CALM2 boosts CAMK2 and arouses the AMPK signaling axis, therefore increasing the proliferation, colony formation, and invasion of gastric cancer cells." (PMID 34604066, 2021). "Moreover, CALM2 has been found to stimulate proliferation, migration, invasion, and angiogenesis of HUVECs, as well as M2 polarization of THP1 cells, through the JAK2/STAT3/HIF-1/VEGFA signaling pathway, thereby facilitating gastric cancer metastasis." (PMID 39695099, 2024).
cardiac arrest (4 papers, 2014 to 2025). Cessation of breathing and/or cardiac function. "The aim of this paper is to describe the clinical manifestations of the Asn98Ser mutation in CALM2 in two unrelated children in southern Spain with apparently cardiac arrest/death (UCA)." (PMID 27100291, 2016). "The aim of this paper is to describe the clinical manifestations of the Asn98Ser mutation in CALM2 in two unrelated children in southern Spain with apparently unexplained cardiac arrest/death." (PMID 27100291, 2016). "For example, using WES calmodulin (CALM1 and CALM2), mutations were discovered as the underlying genetic cause of severe QT-prolongation and recurrent cardiac arrest in infants." (PMID 24972929, 2014). "CALM2 mutations may result in neonatal bradycardia, cardiac arrest at a young age, a markedly prolonged QTc interval and eventually mild neurodevelopmental delay." (PMID 28315637, 2017).
Ventricular arrhythmia (4 papers, 2021 to 2026). "In addition, we identify rhythms in the expression of genes from a range of potential systems that have been linked to ventricular arrhythmias in human and mouse studies, including Calm2, Kcnh2, Scn5a, Cx43, and Cx4538–42." (PMID 33931651, 2021).
epilepsy (3 papers, 2016 to 2025). A brain disorder characterized by episodes of abnormally increased neuronal discharge resulting in transient episodes of sensory or motor neurological dysfunction, or psychic dysfunction. "Calmodulins are important for ion channel activity and signal transduction, and human CALM2 mutations are associated with delayed neurodevelopment and epilepsy." (PMID 41252183, 2025). "Likewise, 12/28 genes have been implicated in epilepsy or have a close family member established to increase risk including SCN2B, CALM1, CALM2, and APP." (PMID 26824476, 2016).
Alzheimer disease (2 papers, 2017 to 2023). A progressive, neurodegenerative disease characterized by loss of function and death of nerve cells in several areas of the brain leading to loss of cognitive function such as memory and language. "Proteins involved in endocytosis, including clathrin-mediated endocytosis (CME) adapters, assembly protein complex 2 (AP-2) and CALM2, control autophagy and regulate the degradation of components of amyloidosis in Alzheimer’s disease." (PMID 35639336, 2023).
Brugada syndrome (2 papers, 2021 to 2023). A genetically heterogeneous condition characterized by complete or incomplete right bundle branch block accompanied by ST elevation in leads V1-V3. "However, the children carrying the CALM2 G114R variant displayed a phenotype commonly observed with variants in NaV1.5, i.e., Brugada Syndrome (BrS) or LQT3, where death while asleep is a common feature." (PMID 37663247, 2023). "Moreover, CALM1 and CALM2 genes have been linked to LQTS and mutations in SCN5A-encoded Nav1.5 correlated with idiopathic ventricular fibrillation (IVF) and Brugada syndrome." (PMID 35004871, 2021).
diabetes (2 papers, 2023). "Calm2 plays a role in signal transduction and has been implicated in diabetes where high expression of Calm2 induced early-onset diabetes or diabetic nephropathy in mice." (PMID 37582711, 2023). "Furthermore, the two signaling nodes in the inter-organ mechanism of IPF proposed in our study, CALM1/CALM2/CALM3 (in the lung) and PCK1 (in the liver), are both molecularly linked to diabetes." (PMID 38081956, 2023).
myocardial infarction (2 papers, 2021 to 2025). Gross necrosis of the myocardium, as a result of interruption of the blood supply to the area, as in coronary thrombosis. "For example, MALAT1 knockout can alleviate acute myocardial infarction through the miR-320/Pten axis, and lncRNA Gas5 targets the miR-525-5p/CALM2 axis to regulate myocardial infarction." (PMID 35005241, 2021). "One study regarding myocardial infarction suggested that by sponging miR-525-5p, GAS5 enhances the expression of calmodulin 2 (CALM2) and induces the apoptosis of myocardial cells, thereby promoting the development and progression of myocardial infarction." (PMID 39941145, 2025).
Obesity (2 papers, 2020 to 2023). Accumulation of substantial excess body fat. "Calm2 encodes calmodulin 2, and its expression was increased in obesity but decreased in ABA and was persistently changed in both conditions." (PMID 37582711, 2023). "CLSTN2 (calmodulin 2) plays an important role in promoting adipocyte proliferation in visceral adipose tissue and subcutaneous fat and is associated with mammalian obesity." (PMID 33391332, 2020). "We then ascertained which genes were altered in opposite directions in these nutritional extremes and found Calm2 to be increased in obesity but decreased in ABA while Vps13d was decreased during obesity yet increased during ABA." (PMID 37582711, 2023).
Parkinson disease (2 papers, 2021 to 2022). A progressive degenerative disorder of the central nervous system characterized by loss of dopamine producing neurons in the substantia nigra and the presence of Lewy bodies in the substantia nigra and locus coeruleus. "From the Parkinson’s disease KEGG enrichment result, five of differently expressed piRNAs-aligned genes (NDUFA4, CALM3, UCHL1, CALM2, and HSPA5) in the prefrontal cortex (15 genes) overlapped with differently expressed piRNAs-aligned genes in the amygdala (16 genes)." (PMID 35269612, 2022).
atherosclerosis (1 paper, 2022). A disease characterized by the build-up of fatty material and calcium deposition in the arterial wall resulting in partial or complete occlusion of the arterial lumen. "Similar to APOB and CD36, the CALM1, CALM2, and CALM3 encoding calmodulin 1, 2, and 3, respectively were differentially expressed and downregulated on the lipid and atherosclerosis pathway." (PMID 36506940, 2022). "The genes that were differentially expressed in the lipid and atherosclerosis pathway were APOB (P = 0.008), CD36 (P = 0.040), CALM1, CALM2, CALM3 (P = 0.015), and HSPA8 (P = 0.047)." (PMID 36506940, 2022).
breast tumors (1 paper, 2010). "It will be particularly important to test the role of HuR upon CD9 and CALM2 expression in breast tumors in vivo." (PMID 20370918, 2010).
endometrial cancer (1 paper, 2021). Primary or metastatic malignant neoplasm involving the endometrium (mucous membrane that lines the endometrial cavity). "The results showed that the expression of CDK1, CALM2, and SIRT4 was significantly increased in all grades of endometrial cancer compared to the control group." (PMID 34768392, 2021).
glioma (1 paper, 2021). A benign or malignant brain and spinal cord tumor that arises from glial cells (astrocytes, oligodendrocytes, ependymal cells). "High expressions of CALD1, CALML4, CALML6, CALM1 and CALM2 were associated with IDH wildtype glioma." (PMID 34070840, 2021). "However, in the CGGA dataset, only CALD1, CALML4 and CALML6 were associated with IDH wildtype glioma, and no specific relationship with CALM3, CALM1 and CALM2 expression was noticed." (PMID 34070840, 2021).